RN7SKP189 (RN7SK pseudogene 189)
Gene: Miscellaneous RNA gene on chromosome X (145,057,108 to 145,057,437, forward strand). Ensembl gene ENSG00000201912.
Homologues: Orthologues: chimpanzee 7SK (99% identical). Paralogues in human: 7SK (74% identical), RN7SKP180 (73% identical), RN7SKP79 (73% identical), RN7SKP176 (73% identical), RN7SKP203 (72% identical), RN7SKP9 (72% identical), RN7SKP250 (72% identical), RN7SKP47 (72% identical), RN7SKP217 (71% identical), RN7SKP187 (71% identical), RN7SKP249 (71% identical), RN7SKP118 (71% identical), and 283 more.